ZWINT (ZW10 interacting kinetochore protein)
Description:
Acts as a component of the outer kinetochore KNL1 complex that serves as a docking point for spindle assembly checkpoint components and mediates microtubule-kinetochore interactions. Kinetochores, consisting of a centromere-associated inner segment and a microtubule-contacting outer segment, play a crucial role in chromosome segregation by mediating the physical connection between centromeric DNA and spindle microtubules. The outer kinetochore is made up of the ten-subunit KMN network, comprising the MIS12, NDC80 and KNL1 complexes, and auxiliary microtubule-associated components; together they connect the outer kinetochore with the inner kinetochore, bind microtubules, and mediate interactions with mitotic checkpoint proteins that delay anaphase until chromosomes are bioriented on the spindle. Targets the RZZ complex to the kinetochore at prometaphase. Recruits MAD2L1 to the kinetochore, but is not required for BUB1B localization (By similarity). In addition to orienting mitotic chromosomes, it is also essential for alignment of homologous chromosomes during meiotic metaphase I (By similarity). In meiosis I, required to activate the spindle assembly checkpoint at unattached kinetochores to correct erroneous kinetochore-microtubule attachments.
Synonyms: KNTC2AP; SIP30; Zwint1; HZwint-1
Tractability: PROTAC: ubiquitination databases record sites on it; its protein half-life has been measured.
Gene: Protein-coding gene on chromosome 10 (56,356,736 to 56,361,392, reverse strand). Ensembl gene ENSG00000122952.
Subcellular location: Nucleus; Chromosome, centromere, kinetochore
Subcellular location (Human Protein Atlas): Nuclear bodies; Nucleoplasm; Cytosol
Pathways (Reactome):
Cell Cycle: Amplification of signal from unattached kinetochores via a MAD2 inhibitory signal; EML4 and NUDC in mitotic spindle formation; Mitotic Prometaphase; Resolution of Sister Chromatid Cohesion; Separation of Sister Chromatids
Signal Transduction: RHO GTPases Activate Formins
Gene Ontology:
Molecular function: protein binding
Biological process: establishment of localization in cell; mitotic sister chromatid segregation; mitotic spindle assembly checkpoint signaling; homologous chromosome orientation in meiotic metaphase I; regulation of meiosis I spindle assembly checkpoint
Cellular component: cytoplasm; cytosol; kinetochore; Knl1/Spc105 complex; nuclear body; nucleoplasm; nucleus; outer kinetochore; dendrite
Genetic constraint (gnomAD): Loss-of-function variants: 41 observed, 42.64 expected, observed/expected ratio (o/e) 0.96, 90% interval 0.75 to 1.25. The upper end of that interval is the gene's LOEUF score, 1.25, which puts it in group 5 of 6, group 1 being the genes least tolerant of losing a copy. Missense variants: 369 observed, 339.06 expected, observed/expected ratio (o/e) 1.09, 90% interval 1 to 1.19. Synonymous variants: 132 observed, 133.98 expected, observed/expected ratio (o/e) 0.99, 90% interval 0.85 to 1.14.
Homologues: Orthologues: chimpanzee ZWINT (98% identical), macaque ZWINT (96% identical), pig ZWINT (74% identical), rabbit ZWINT (70% identical), guinea pig ZWINT (61% identical), dog ZWINT (53% identical), rat Zwint (50% identical), mouse Zwint (50% identical).
Diseases named in the same sentence as ZWINT in open-access papers:
ZWINT is named in the same sentence as 48 diseases in open-access papers, as found by Europe PMC text mining. Sharing a sentence is not in itself a finding about the gene and the disease. The quoted sentences say what the papers report.
lung carcinoma (13 papers, 2019 to 2025). "The results demonstrated that there was no direct mutual exclusion or co-expression relationship between mutations of FAM111B and ZWINT and common mutations of lung cancer." (PMID 35406786, 2022). "Using cbioportal tool, the mutations of FAM111B and ZWINT in 3513 patient samples were compared with those closely related to lung cancer driver genes from 10 databases, including TCGA." (PMID 35406786, 2022). "Some of the predicted master regulators, including PTTG1, RFC4, TRIP13, BUB1B, TTK, and ZWINT are capable of promoting migration, invasion, and metastasis of lung cancer cells." (PMID 36304306, 2022). "Reported studies suggested that ZWINT was highly expressed in various cancers and related with cancer progress, such as lung cancer and liver cancer." (PMID 34384030, 2021). "Increased expression of ZWINT correlates with poor outcomes in human malignancies, including prostate, ovarian, bladder and lung cancers." (PMID 31572440, 2019). "The AFAP1-AS1/miR-508-3p/ZWINT axis contributes to key oncogenic processes including cell proliferation, apoptosis suppression, and invasion, underscoring its potential as a novel therapeutic target in lung cancer." (PMID 40650307, 2025). "ZWINT appears as a hub gene in our PPI network and encodes a fundamental component of the mitotic checkpoint and has been previously implicated in overall and disease-free survival of lung cancer." (PMID 37924098, 2023). "ZWINT is also related to the pathological mechanism of lung cancer and may serve as a new biomarker." (PMID 34852139, 2021). "Notably, ZWINT was overexpressed in multiple tumors such as HCC, prostate, and lung cancer, and it was associated with poor survival through upregulating cell-cycle proteins." (PMID 33221765, 2020).
breast cancer (10 papers, 2019 to 2025). A primary or metastatic malignant neoplasm involving the breast. "Collectively, these results suggested that ZWINT expression has a close correlation with gene mutations in breast cancer." (PMID 40591167, 2025). "ZWINT expression was lower in tumor specimens from CDH1-mutant breast cancer patients (total mutation rate: 14.096%)." (PMID 40591167, 2025). "Multi-omics analysis revealed a strong association between ZWINT expression and metastatic processes across breast cancer subtypes." (PMID 41046283, 2025). "ZWINT overexpression is notably associated with reduced OS, RFS, and DMFS in breast cancer patients, and ZWINT has the potential to serve as an independent prognostic marker in the patients." (PMID 40591167, 2025). "We systematically characterized the spatial expression pattern of ZWINT across various breast cancer subtypes and assessed its prognostic significance using an integrated bioinformatics approach that involved multi-omics analysis." (PMID 40591167, 2025). "Functionally, ZWINT knockdown significantly inhibited breast cancer cell migration and invasion in vitro and dramatically reduced lung metastasis in vivo." (PMID 41046283, 2025). "Analysis of the TNMplot database revealed significant differential expression of ZWINT across breast cancer progression stages." (PMID 40591167, 2025). "This study systematically investigated the clinical significance of ZWINT expression in breast cancer through integrated molecular subtyping and survival analysis." (PMID 40591167, 2025). "The analyzed data indicate that high ZWINT expression is associated with reduced OS across various cancer types, and ZWINT alongside other genes can enhance predictions regarding the survival of breast cancer patients." (PMID 40591167, 2025). "In summary, our data analysis reveals that ZWINT is overexpressed at both the transcriptional and protein levels in patients with breast cancer." (PMID 40591167, 2025). "Consistent with other findings, basal-like breast cancer patients demonstrated significantly elevated ZWINT expression levels (0.4245 ± 0.8502, n = 1880) compared to non-basal-like cases (−0.0868 ± 0.9233, n = 8036) (P < 0.0001)." (PMID 40591167, 2025). "ZWINT expression was higher in breast cancer tissues than in healthy breast tissues according to the earlier research." (PMID 40591167, 2025). "Our findings demonstrate that ZWINT drives breast cancer metastasis and is negatively regulated by miR-495-3p." (PMID 41046283, 2025). "In this work, we comprehensively analyzed the data from multiple web-based genomic databases and observed consistently elevated expression of ZWINT mRNA and protein in breast cancer with various clinicopathological characteristics." (PMID 40591167, 2025). "Initial analysis revealed significantly elevated ZWINT expression in breast cancer (median transcripts per million [TPM] = 5.15) compared to normal breast tissue (median TPM = 2.09)." (PMID 40591167, 2025). "Among the various molecular players involved in breast cancer progression, ZWINT has emerged as a key regulator." (PMID 40591167, 2025). "Our analysis revealed consistent upregulation of ZWINT mRNA and protein expression across distinct clinicopathological subtypes of breast cancer." (PMID 40591167, 2025). "The highest levels of RRM2 and ZWINT were found in HER2-positive breast cancer, and the highest expression of other hub genes was found in triple-negative breast cancer." (PMID 36200070, 2022).
breast cancer (continued). "ZWINT was recently reported to be an oncoprotein in multiple cancer types, including glioblastoma, breast cancer, lung adenocarcinoma." (PMID 34900978, 2021). "Consequently, further experimental validation of the mechanisms by which ZWINT affects tumor metastasis and its multi-gene prognostic significance in breast cancer patients is essential." (PMID 40591167, 2025). "In addition, our present analysis indicated that ZWINT expression levels were reduced in CDH1-mutant breast cancer patients compared to those with the wild-type." (PMID 40591167, 2025). "The newly identified miR-495-3p/ZWINT/p38 MAPK axis may provide a promising therapeutic target for suppressing breast cancer progression." (PMID 41046283, 2025). "Our data also suggest ZWINT may represent a promising target for the development of anti-ZWINT therapies in addition to being an effective prognostic indicator for breast cancer." (PMID 40591167, 2025). "Additionally, HPA indicated that ZWINT protein expression was elevated in breast cancer tissues compared to normal tissues." (PMID 40591167, 2025). "To evaluate the prognostic significance of ZWINT expression in breast cancer, we analyzed its correlation with patient survival outcomes, including overall survival (OS), relapse-free survival (RFS), distant metastasis-free survival (DMFS), and progress-free survival (PPS)." (PMID 40591167, 2025). "Nevertheless, whether the expression levels of ZWINT are significantly correlated with clinicopathological characteristics and prognostic outcomes of patients with breast cancer remains elusive." (PMID 40591167, 2025). "Furthermore, ZWINT emerged as an independent prognostic factor for breast cancer through both univariate and multivariate Cox regression analyses." (PMID 40591167, 2025). "Notably, studies have shown a strong correlation between elevated ZWINT expression and advanced tumor staging, suggesting its involvement in breast cancer metastasis and disease progression." (PMID 40591167, 2025). "Furthermore, the bc-GenExMiner 5.1 tool was utilized to explore the expression profile of ZWINT across various PAM50 breast cancer subtypes, taking into account different clinicopathological parameters." (PMID 40591167, 2025). "Additionally, ZWINT was found to be a useful independent prognostic marker for breast cancer using Cox regression analysis." (PMID 40591167, 2025). "Recent studies have indicated that ZWINT-1 may function as a biomarker for cancer due to its high expression in some human malignancies such as glioblastoma, breast cancer, ovarian cancer, bladder cancer, lung cancer, and hepatocellular carcinoma." (PMID 34900978, 2021). "Currently, little is known about the role of ZW10 interactor (ZWINT) in breast cancer." (PMID 34675265, 2021). "KCNK1 expression was positively correlated with that of LDHA, Pan Kla, ZWINT, ECT2, ANLN, and EZR, reconfirming that KCNK1 played an important role in the proliferation and metastasis of breast cancer." (PMID 38905316, 2024). "ChIP-qPCR also showed that overexpression of LDHA blocked the inhibitory effect of KCNK1 knockdown on H3K18la and p300 binding of ZWINT, ECT2, ANLN, EZR, and LDHA in breast cancer cells." (PMID 38905316, 2024). "Though previous reports show an association between ZWINT overexpression and triple-negative breast cancers, the functional role of ZWINT and ECT in breast cancer remains largely unexplored." (PMID 35948941, 2022). "However, the expression profiles of ZWINT across different breast cancer subtypes have not been comprehensively characterized." (PMID 40591167, 2025).
liver cancer (5 papers, 2017 to 2023). An epithelial or non-epithelial malignant neoplasm that arises from the liver. "The high expression of ZWINT is strongly associated with tumor recurrence, which is a possible risk factor for the high recurrence rate and poor survival rate in patients with liver cancer." (PMID 37091844, 2023). "Then, immunohistochemistry staining validated from the Human Protein Atlas database showed that ZWINT, NCAPG and CENPF protein expression were strongly upregulated in liver cancer tissues compared with normal tissues." (PMID 31410310, 2019). "We found that BIRC5, CDK1, NUF2, ZWINT, and SPC24 were highly expressed in liver cancer tissues, whereas expression was weak in normal tissues." (PMID 29190974, 2017). "Moreover, among of them, RFC4, ZWINT, UPF3B, NCBP2, ADA, SF3A3 and GTF2H1 are independent prognostic indicators of liver cancer." (PMID 33516217, 2021).
lung adenocarcinoma (5 papers, 2020 to 2025). A carcinoma that arises from the lung and is characterized by the presence of malignant glandular epithelial cells. "Furthermore, Kaplan–Meier survival assessments revealed that high ZWINT expression was associated with poor overall survival in lung adenocarcinoma patients." (PMID 40650307, 2025). "The invasive potential of lung adenocarcinoma cells was reversed in the presence of overexpression of ZWINT, thus demonstrating the applicability of intervention in limitation of tumor metastasis using the AFAP1-AS1/miR-508-3p/ZWINT axis." (PMID 40650307, 2025). "Evenly, while we found a potential target (ZWINT) of miR-508-3p, more studies should be carried out to comprehensively understand the molecular roles of miR-508-3p and ZWINT in the progression of lung adenocarcinoma." (PMID 40650307, 2025). "This study investigates the functional role of AFAP1-AS1 in lung adenocarcinoma cell proliferation via miR-508-3p and ZWINT." (PMID 40650307, 2025). "In conclusion, our study revealed that AFAP1-AS1 plays a critical role in promoting the progression of lung adenocarcinoma through its interaction with miR-508-3p and subsequent regulation of ZWINT." (PMID 40650307, 2025). "AFAP1-AS1 accelerates the development of lung adenocarcinoma by cell proliferation, apoptosis, and invasion via the miR-508-3p/ZWINT axis." (PMID 40650307, 2025). "This study mainly explored the relationship between the expression level of ZWINT and the prognosis of patients with lung adenocarcinoma (LUAD)." (PMID 34852139, 2021). "Furthermore, ZWINT, identified as a target of miR-508-3p, was significantly upregulated in lung adenocarcinoma tissues." (PMID 40650307, 2025). "Notably, ZWINT was the only target that showed significant (p < 0.05) upregulation in lung adenocarcinoma tissues relative to normal tissues, as retrieved from the GEPIA database." (PMID 40650307, 2025). "In our experiment, overexpression of ZWINT reversed the inhibitory roles of AFAP1-AS1 knockdown on the proliferation and invasion of A549 cells, and this evidence suggests that AFAP1-AS1 may contribute to lung adenocarcinoma progression through the miR-508-3p/ZWINT axis." (PMID 40650307, 2025).
ovarian carcinoma (5 papers, 2019 to 2022). A malignant neoplasm originating from the surface ovarian epithelium. "In one previous study, 4 of 16 identified hub genes in the studied sample (CCNB1, CENPF, KIF11, and ZWINT) were associated with decreased OS of patients with ovarian cancer." (PMID 34785763, 2022). "Recently, ZWINT overexpression has been reported in ovarian cancer and hepatocellular carcinoma, and it is intimately linked to tumor progression and a poor prognosis." (PMID 36247089, 2022). "The gene encoding this protein, ZWINT, was discovered to be overexpressed in ovarian cancer, among other genes (such as CCNB1, CENPF, KIF11) related with cell cycle, nuclear division and oocyte meiosis." (PMID 33445445, 2021). "Univariate and multivariate analyses of the correlation of CDCA5, FOXM1, KIF15, MCM2, and ZWINT expression with overall survival (OS) among epithelial ovarian cancer patients." (PMID 31708970, 2019).
pancreatic cancer (5 papers, 2020 to 2022). "To clarify the mechanisms by which ZWINT promotes pancreatic cancer progression, we analyzed the pathways associated with ZWINT using the TCGA database." (PMID 34900978, 2021). "In pancreatic cancer, knocking down ZWINT down-regulated NF-κB regulatory genes and effectively reduced the invasion and migration ability of cancer cells." (PMID 35406786, 2022). "Kim JH found that ZWINT was upregulated in pancreatic cancer and promoted pancreatic cancer progression." (PMID 34900978, 2021). "Our data showed that hypoxia promoted the expression of ZWINT in pancreatic cancer, and ZWINT promoted pancreatic cancer proliferation in vitro and in vivo." (PMID 34900978, 2021). "To determine whether tumor growth is affected by ZWINT in vivo, we established a xenograft mouse model by subcutaneously injecting pancreatic cancer cells overexpressing ZWINT or controls into mice (n = 5, each group)." (PMID 34900978, 2021). "Together these data indicate that ZWINT promoted pancreatic cancer growth in vivo." (PMID 34900978, 2021). "Consistent with the previous results, ZWINT could positively drive the pancreatic cancer cell cycle turning over." (PMID 34900978, 2021). "In addition, knockdown of ZWINT-1 restrained the proliferation, migration, invasion, and colony formation abilities of pancreatic cancer cells and increased cell apoptosis." (PMID 34900978, 2021). "The results indicated that ZWINT was significantly upregulated in pancreatic cancer tissue." (PMID 34900978, 2021). "ZWINT was overexpressed in pancreatic cancer and induced in hypoxia." (PMID 34900978, 2021). "However, the role of ZWINT in pancreatic cancer has remained unknown." (PMID 34900978, 2021).
hepatocellular carcinoma (4 papers, 2013 to 2024). A malignant tumor that arises from hepatocytes. "Overexpression of ZWINT predicts poor prognosis and promotes the proliferation of hepatocellular carcinoma." (PMID 39189258, 2024). "Overexpression of ZWINT predicts poor prognosis and promotes the proliferation of hepatocellular carcinoma by regulating cell-cycle-related proteins." (PMID 33516217, 2021).
glioblastoma (3 papers, 2021 to 2022). The most malignant astrocytic tumor (WHO grade IV). "Conversely, ZWINT knockdown effectively inhibits proliferation of glioblastoma cells in vitro and suppresses glioblastoma growth in vivo." (PMID 34069831, 2021). "ZW10 interacting kinetochore protein (ZWINT) and Epithelial cell transforming 2 (ECT), both mitotic checkpoint proteins, have been shown to contribute to poor prognosis across multiple cancer types including glioblastoma." (PMID 35948941, 2022).